ICAM1 (intercellular adhesion molecule 1)
Diseases named in the same sentence as ICAM1 in open-access papers (continued):
Sharing a sentence is not in itself a finding about the gene and the disease.
diabetic retinopathy (continued). "The results suggest that the effective component extract of Coreopsis tinctoria Nutt can prevent and treat diabetic retinopathy by downregulating the expressions of VEGF and ICAM1, and the combination of metformin and Coreopsis tinctoria Nutt has a better effect." (PMID 34691233, 2021). "The previous study indicates that the ethyl acetate extract of Coreopsis tinctoria Nutt may play a certain protective effect on diabetic retinopathy by downregulating the expressions of VEGF and ICAM1." (PMID 34691233, 2021). "NFAT inhibition also reduced ICAM-1 mRNA levels in retinal microvessels, highlighting a potential mechanism by which NFAT inhibition may prevent leukostasis and inflammation in diabetic retinopathy." (PMID 25918731, 2015). "Diabetic retinopathy is a multifactorial disease that is associated with not only VEGF, but also other inflammatory cytokines, such as monocyte chemoattractant protein-1, intercellular adhesion molecule 1, interleukin-6, and platelet-derived growth factor." (PMID 37374329, 2023). "VEGF-mediated upregulation of ICAM-1, an adhesion receptor for leukocytes, may contribute to the observed retinal vascular changes, such as vascular leakage and local nonperfusion in early diabetic retinopathy." (PMID 21139695, 2010). "Importantly, diabetic Cd40−/− mice are protected from retinal upregulation of intercellular adhesion molecule 1 (ICAM-1), TNF-α, IL-1β, nitric oxide synthase 2 (NOS2) and C-C motif chemokine ligand 2 (CCL2) and do not develop diabetic retinopathy." (PMID 35920844, 2022).
Insulin resistance (56 papers, 2011 to 2026). Increased resistance towards insulin, that is, diminished effectiveness of insulin in reducing blood glucose levels. "Relevant studies have pointed out the elevation of ICAM-1 is closely linked with the process of insulin resistance." (PMID 38084239, 2023). "The primary objective of this study was to compare the effects of aerobic exercise and yoga on endothelial function, measured by ICAM-1, and insulin resistance, measured by HOMA-IR, in adults with T2DM and BMI ≥23 kg/m2." (PMID 40978826, 2025). "Several mechanisms have been reviewed regarding the glucose-lowering effects of biologics, including reduced TNFα-induced insulin resistance, reduced soluble ICAM1 levels, and increased high-molecular-weight adiponectin." (PMID 38842591, 2024). "ICAM-1 is an inflammatory factor that participates in the adhesion of monocytes and lymphocytes to endothelial cells and mediates the process of insulin resistance through inflammation." (PMID 38084239, 2023). "Insulin resistance also contributes to elevated levels of proinflammatory markers and ROS, leading to increased intracellular levels of adhesion molecule-1 (ICAM-1) and VCAM-1 in endothelial cells." (PMID 37189834, 2023). "Intercellular adhesion molecule 1 (ICAM-1) induces a proinflammatory and proatherogenic response in atherosis, insulin resistance, and the development of coronary disease." (PMID 36636607, 2023). "As a matter of fact, it was reported that ICAM-1 levels can be influenced by age, insulin resistance and other inflammatory conditions." (PMID 33299020, 2020). "We found that plasma levels of visfatin, vaspin, VCAM-1, ICAM-1, E-selectin, and Ang-2 were similar in the insulin resistance and non-insulin resistance groups." (PMID 31771561, 2019). "WD-fed Icam1tmBay mice exhibited an increased insulin resistance and systemic inflammation, as evidenced by worsened glucose tolerance and increased circulating neutrophils and TNFα, suggesting a protective effect of ICAM-1 against metabolic dysregulation." (PMID 40670579, 2025). "Palmitic acid induces mitochondrial damage and mtDNA into the cytosol to activate STING-IRF3 pathway and to promote the level of ICAM-1 further to aggravate insulin resistance, obesity and glucose intolerance, implying STING as a candidate for insulin resistance." (PMID 39183465, 2024). "During the process of metabolic stress–induced endothelial inflammation and insulin resistance, palmitic acid caused mtDNA leakage into the cytoplasm, and activated STING signaling to mediate the intercellular adhesion molecule (ICAM)-1 expression and endothelial inflammation." (PMID 30984149, 2019). "This response was associated with an improvement in lipoprotein profile and insulin resistance, coupled with a decrease in acute-phase inflammatory proteins, such as hs-CRP and C3, and a reduction in levels of pro-atherosclerotic molecules, such as PAI-1 and ICAM-1." (PMID 39061938, 2024). "Using an in vivo model of human insulin resistance, we went on to show that complete and long-term genetic deletion of the Nox2 isoform leads to increased lipid deposition in the thoraco-abdominal aorta, substantial damage to the aortic wall, and increased expression of the adhesion molecule ICAM-1." (PMID 32401607, 2020). "Furthermore, in STZ-induced T2D rat model, compared with diabetic control groups, CA remarkably downregulated the levels of serum lipid, blood glucose, ICAM-1, malonaldehyde and insulin resistance index, while upregulated SOD activity and impaired glucose tolerance." (PMID 30867526, 2019). "The ICAM-1 glycoprotein may facilitate migration of leukocytes from the blood to the adipose tissue, which could result in local inflammation and subsequently insulin resistance." (PMID 27219535, 2016). "NFκB activation further induces the release of pro-inflammatory cytokines such as IL-6, TNFα, ICAM-1, and VCAM-1, which ultimately exacerbates insulin resistance in diabetic patients." (PMID 40369521, 2025).
Insulin resistance (continued). "Measurements of fasting blood sugar (FBS), HbA1c, insulin resistance (homeostatic model assessment for insulin resistance (HOMA-IR)), and endothelial function by intracellular adhesion molecule-1 (ICAM-1) levels were taken before and after the intervention." (PMID 40978826, 2025). "Third, treating mice, which are both deficient in ApoE and display endothelium-specific insulin resistance, with the Nox2-specific inhibitor gp91dstat reduced superoxide generation and deposition of lipid in the thoraco-abdominal aorta without elastin fragmentation or increasing ICAM-1 expression." (PMID 32401607, 2020). "Early phase of NAFLD, characterized by significant liver steatosis and prominent insulin resistance, was related with LSEC pro-inflammatory phenotype as evidenced by elevated ICAM-1, E-selectin and PECAM-1 expression." (PMID 30809151, 2019). "High levels of CRP are also involved in the production of adhesion molecules, namely, E-selectin, ICAM-1, and VCAM-1, which play a role in vascular endothelial dysfunction, insulin transport reduction, and peripheral insulin resistance." (PMID 31485456, 2019). "Triglycerides, insulin, homeostasis model assessment-insulin resistant (HOMA-IR), leptin, C-reactive protein (CRP), and EDF marker intercellular adhesion molecule 1 (ICAM-1) were significantly higher in obese children and adolescents." (PMID 30572569, 2018). "Inflammatory factors such as adhesion molecules (ICAM-1 and VCAM-1), CD40 ligands, C-reactive protein (CRP) and myeloperoxidase (MPO) participate in induction of insulin resistance and atherosclerotic disease." (PMID 21247435, 2011). "The role of magnesium sulfate (MgSO4) administration to prevent diabetic nephropathy (DN) by reducing insulin resistance (IR) and the relationship of this action with gender and the expression of NOX4 and ICAM1 genes in the parents and their offspring were studied." (PMID 36755074, 2023). "To validate this results, we assessed the modulation of ICAM1, NQO1, IGFBP3, and THBS1 by POPs because, in addition to their role in cell adhesion, xenobiotic metabolism, angiogenesis, and cancer, these genes were reported to be related to adiposity, insulin resistance, and inflammation." (PMID 22262711, 2012). "Furthermore, in the women with insulin resistance, intake of MOJ for 4 weeks reduced the plasma VCAM-1 levels (554.99 ± 15.63 to 545.31 ± 14.65 ng·mL−1, p = 0.039) but the plasma levels of ICAM-1, C-reactive protein, TNF-α, IL-6, and IL-10 were not significantly altered." (PMID 37469434, 2023).
coronary heart disease (52 papers, 2007 to 2026). "There is mounting evidence suggesting that elevated levels of soluble E‐selectin, VCAM1, and/or ICAM1 in circulation are linked to the severity and complications of coronary artery disease." (PMID 39040847, 2024). "This study aimed to investigate the association of K469E polymorphism of the ICAM-1 gene and soluble ICAM-1 (sICAM-1) serum level with coronary heart disease (CHD) in Egyptian subjects." (PMID 20940515, 2010). "For example, in some groups of depressed patients, lower ICAM-1 levels may reduce the risk of coronary disease." (PMID 37921965, 2023). "Associations between VCAM-1 levels and 2-day average black carbon (BC) exposures have also been reported, as well as between longer BC exposure averages (4–12 weeks) and ICAM-1, and lastly 1–2 day lagged associations between EC and ICAM-1 in coronary heart disease patients." (PMID 24314116, 2013). "In fact, C. pneumoniae infection induced cytokines, E-selectin, ICAM-1, and VCAM-1 expression in endothelial cells; the patients suffering from coronary artery disease had a higher plasma level of ICAM-1 and E-selectin, which was associated with Chlamydia IgA LPS seropositivity." (PMID 22900050, 2012). "Interestingly, an interaction between another ICAM1 non-synonymous SNP (rs5498, r2 = 0.17 with rs1799969) and smoking was recently described with regards to susceptibility to coronary artery disease." (PMID 20585554, 2010). "For instance, elevated levels of C-reactive protein, IL-6, ICAM-1, VCAM-1, and E-selectin have been consistently linked to various atherosclerotic manifestations, including peripheral vascular disease, ischemic heart disease, and acute myocardial infarction." (PMID 39851572, 2025). "Human malignancies and inflammatory disorders (including coronary artery disease and airway inflammation) have higher levels of soluble intercellular adhesion molecule 1 (sICAM-1), which is generated when the ICAM-1 cell surface is broken by proteases." (PMID 41179937, 2025). "Four clinical studies were eligible.According to Tavakoli-Rouzbehani et al25 reported that 2 g/day N. sativa oil for 8 weeks considerably decreased serum VCAM-1 and ICAM-1 in coronary artery disease patients compared with the control patients." (PMID 40365513, 2025). "A single LDL apheresis session was able to significantly reduce E-selectin, VCAM-1 and ICAM-1 levels in patients with coronary arterial disease." (PMID 38398435, 2024). "Preliminary evidence indicated that L-carnitine and its metabolites by inhibitory effects on expressing adhesion molecules, like ICAM-1 during the inflammatory process, such as coronary heart diseases, can exhibit a myocardial protection effect." (PMID 35936217, 2022). "Coronary heart disease is related to sudden death caused by multi-factors and a major threat to human health.This study explores the role of OX40L and ICAM-1 in the stability of coronary plaques and their relationship with sudden coronary death." (PMID 31783796, 2019). "Recently, a robust, real time, label-free SPR biomarker detection platform for ICAM-1(+) nEVs was developed for predicting the existence and stage of coronary heart disease (CHD)." (PMID 31134179, 2019). "Accumulating evidence has revealed that ICAM-1 and VCAM-1 polymorphisms correlate to myocardial infarction and coronary artery disease." (PMID 33817202, 2019). "Higher levels of plasma intercellular adhesion molecule-1 (ICAM-1), vascular cell adhesion molecule-1 (VCAM-1), and E-selectin in community-dwelling subjects and in coronary arterial disease patients are associated with C. pneumoniae seropositivity." (PMID 24376840, 2013). "Evidences support a crucial role for C. pneumoniae seropositivity, as it associated with a higher level of plasma ICAM-1 and VCAM-1 in the general population and a higher level of plasma ICAM-1 and E-selectin in coronary arterial disease patients." (PMID 22900050, 2012).
coronary heart disease (continued). "Several genomewide association studies (GWASs) have identified ABO as a candidate marker of the risk for coronary artery disease (CAD), in addition to established CAD markers (sE-selectin, sP-selectin, and s-ICAM1)." (PMID 22963146, 2012). "In addition, activation of ICAM-1 also increased the expression of inflammatory genes correlated with coronary heart disease, such as IL-1B40, CXCL8, CCL541, and VCAM-143." (PMID 33758323, 2021). "They found an increased concentration of ICAM-1, which is an adhesion molecule involved in monocyte attachment and transformation to macrophages in the vascular wall and appears an independent predictor of coronary heart disease." (PMID 22952728, 2012). "This study was aimed to explore the correlation of intercellular adhesion molecule‐1 (ICAM‐1) K469E and megakaryoblastic leukaemia factor‐1 (MKL‐1) −184C/T polymorphisms with the susceptibility to coronary heart disease (CHD) in the Chinese Han population." (PMID 32770617, 2020). "The absence of a positive correlation between OSM and ICAM-1, E-selectin and P-selectin may be caused by statin use in the AGES‐Reykjavik study (approx. 22%), as statins reduce ICAM-1, E-selectin and P-selectin plasma levels in patients with coronary artery disease." (PMID 31461490, 2019). "As shown in previous studies, the blood levels of intercellular adhesion molecule-1 (ICAM-1) are recognized to be a marker of coronary artery atherosclerosis and the progression of coronary heart disease (CHD)." (PMID 36440000, 2022). "However, whether ICAM-1 is related to the severity of coronary artery disease is yet controversial." (PMID 31783796, 2019). "In one study, this adipocyte-derived secretory protein inhibited TNFα-induced expression of ICAM-1 and VCAM-1, and its circulating levels were lower in patients with coronary disease." (PMID 27459718, 2016). "Previous studies have demonstrated that a number of inflammatory factors are involved in the course of coronary heart disease, such as IL, TNF-α and ICAM-1." (PMID 24396397, 2014). "Notably, adhesion molecules like ICAM-1 and VCAM-1 have shown promise in predicting the onset of coronary heart disease." (PMID 39851572, 2025). "The previous literature showed that consumption of high fat diet caused deposition of inflammatory cells, lipid infiltration and localization of Intercellular Adhesion Molecule-1 (ICAM-1) and Vascular Cell Adhesion Molecule-1 (VCAM-1) that are key indicators of coronary heart diseases." (PMID 36276841, 2022). "It has been reported that the consumption of a high-fat diet (HFD) caused deposition of inflammatory cells, lipid infiltration and localization of Intercellular Adhesion Molecule-1 (ICAM-1) and Vascular Cell Adhesion Molecule-1 (VCAM-1), which are key indicators of coronary heart diseases." (PMID 36276841, 2022). "As one of the highest incidences of CVDs, coronary artery disease links with more than 20 targets in this T-cD network, such as VCAM1 and ICAM1 (reported to increase in dysfunctional endothelial cells), MMP9, MMP3, and MMP2 (being influencing factors in cardiac fibrosis)." (PMID 29861771, 2018). "ICAM-1 and E-selectin (but not vascular cell adhesion molecule 1) have also been shown to predict carotid artery atherosclerosis and development of coronary heart disease." (PMID 28051279, 2016).
glioma (50 papers, 2012 to 2025). A benign or malignant brain and spinal cord tumor that arises from glial cells (astrocytes, oligodendrocytes, ependymal cells). "We also found that ICAM-1 was related to the glioma-associated macrophages involved in the glioma cells’ resistance to antiangiogenic therapy." (PMID 29228586, 2017). "Our data indicated that up-regulation of VEGF and ICAM-1 is associated with the pathological features of gliomas migration." (PMID 26473373, 2015). "Besides, ICAM-1 was linked to the GAMs embroiled in resistance of glioma to antiangiogenic treatment." (PMID 34368156, 2021). "Radiation also upregulates the expression of intercellular adhesion molecule-1 (ICAM-1), which is expressed in some gliomas and binds to LFA-1 on the surface of iNKT cells." (PMID 40730675, 2025). "The concept of GCM camouflage was inspired by the glioma cells’ ability to easily traverse the BBB by overexpressing intercellular adhesion molecule-1 (ICAM-1) and down-regulating specific proteins in tight junctions." (PMID 39911305, 2025). "Glial Tumors Group: Notably, E-Selectin, ICAM-1, PAI-1, MMP-9, and eNOS were expressed predominantly, whereas VCAM-1 showed lower expression, and P-Selectin was not expressed." (PMID 38306519, 2024). "Here we present evidence for the stem cell marker prominin-1 and the chemotherapeutic target ICAM-1 in a glioma animal model and GBM pathology sections from patients that elicited alternative responses to adjuvant chemotherapy." (PMID 38258133, 2024). "Among these ligands, OSM and ICAM1 have been previously identified as potent molecules inducing MES phenotype transition in glioma cells." (PMID 38398231, 2024). "Along the same lines, ICAM-1 was detected on EVs produced by glioma cells, and DCs loaded with these EVs were able to activate T cells to become CTLs (cytotoxic T lymphocytes) that displayed vigorous cytotoxic activity against glioma cells." (PMID 38542421, 2024). "Treatment of human umbilical vein ECs (HUVECs) with CM from oHSV-infected glioma cells increased expression of EC activation surface receptors: CD54 (ICAM1), CD106 (VCAM1), and CD62P (P-selectin)." (PMID 36789106, 2023). "Mutant IDH1 (IDH1-mut) glioma cells downregulate ICAM1 via ICAM1 promoter methylation resulting in an increased expression of LAMP1 (CD107a), a lysosome-associated membrane protein which has a key role in the formation of phagolysosomes (Molecular event 24)." (PMID 36555253, 2022). "ICAM-1, which is activated by pSTAT3 in hypoxic sites, facilitates glioma cell passage and carcinoma evolution." (PMID 34368156, 2021). "In glioma, it was shown that radiation increased ICAM1 expression, thereby, promoting migration and invasion of the tumor cells." (PMID 31467533, 2019). "We found that ICAM-1 is expressed in several glioma stem cell lines and that ICAM-1 knockdown increases glioma cells’ sensitivity to antiangiogenic therapy." (PMID 29228586, 2017). "In the present study, we found that ICAM-1 is overexpressed in glioma that has developed resistance to antiangiogenic therapy." (PMID 29228586, 2017). "Next, we sought to identify the factors that results in the induction of ICAM1 expression in glioma stem cells." (PMID 29228586, 2017). "A more recent study showed that ICAM-1 expression in glioma was upregulated by the activation and interaction of nuclear factor-κB and STAT3 and mediated tumor cell invasion and migration in response to radiotherapy." (PMID 29228586, 2017). "The expressions levels of VEGF and intracellular adhesion molecule-1 (ICAM-1) were increased in the migration-prone sublines as well as in samples from patients with high-grade glioma when compared to those with low-grade glioma." (PMID 26473373, 2015). "We further investigated the VEGF and ICAM-1 mRNA expression levels from samples of patients with low-grade and high-grade glioma." (PMID 26473373, 2015). "ICAM-1 was also overexpressed in bevacizumab-resistant glioma stem cells in hypoxic circumstances." (PMID 39050471, 2024).